ZFAND3 (zinc finger AN1-type containing 3)
Synonyms: TEX27; FLJ13222
Tractability: No criterion of Open Targets' tractability assessment is met for any kind of drug.
Gene: Protein-coding gene on chromosome 6 (37,819,429 to 38,154,624, forward strand). Ensembl gene ENSG00000156639.
Subcellular location (Human Protein Atlas): Nucleoplasm; Vesicles
Gene Ontology:
Molecular function: protein binding; DNA binding; zinc ion binding
Genetic constraint (gnomAD): Loss-of-function variants: 10 observed, 22.87 expected, observed/expected ratio (o/e) 0.44, 90% interval 0.27 to 0.74. The upper end of that interval is the gene's LOEUF score, 0.74, which puts it in group 3 of 6, group 1 being the genes least tolerant of losing a copy. Missense variants: 189 observed, 211.25 expected, observed/expected ratio (o/e) 0.89, 90% interval 0.79 to 1.01. Synonymous variants: 99 observed, 86.75 expected, observed/expected ratio (o/e) 1.14, 90% interval 0.97 to 1.35.
Homologues: Orthologues: chimpanzee ZFAND3 (100% identical), macaque ZFAND3 (99% identical), dog ZFAND3 (99% identical), pig ZFAND3 (98% identical), rabbit ZFAND3 (98% identical), mouse Zfand3 (96% identical), rat Zfand3 (85% identical), tropical clawed frog zfand3 (80% identical), guinea pig ZFAND3 (79% identical), zebrafish zfand3 (65% identical). Paralogues in human: ZFAND5 (25% identical), ZFAND6 (22% identical).
Diseases named in the same sentence as ZFAND3 in open-access papers:
ZFAND3 is named in the same sentence as 8 diseases in open-access papers, as found by Europe PMC text mining. Sharing a sentence is not in itself a finding about the gene and the disease. The quoted sentences say what the papers report.
glioblastoma (2 papers, 2020 to 2025). The most malignant astrocytic tumor (WHO grade IV). "Interestingly, when overexpressed, ZFAND3 accumulates in the nucleus and increases the invasive capacity of noninvasive glioblastoma stem-like cells (GBMSCs), demonstrating the tumorigenic potential of ZFAND3." (PMID 39779978, 2025). "In GBMSCs expressing epitope-tagged ZFAND3, a few proteasome subunits are coimmunoprecipitated, which may suggest the involvement of proteasome activity in the invasive capacity of glioblastoma." (PMID 39779978, 2025).
type 2 diabetes (2 papers, 2020). "ZFAND3 (also known as testis expressed sequence 27, Tex27) was initially characterized during mouse sperm maturation and was associated with susceptibility for development of type 2 diabetes in humans." (PMID 33311477, 2020).
acute lymphoblastic leukemia (1 paper, 2023). Leukemia with an acute onset, characterized by the presence of lymphoblasts in the bone marrow and the peripheral blood. "Similarly, a ZFAND3–DGKH translocation, retaining the catalytic DGK domain, was documented in Philadelphia-like acute lymphoblastic leukemia." (PMID 37509516, 2023).
tumor (3 papers, 2017 to 2022). "ATP2A2 and ARID5B were identified as being correlated with the GH change rate in response to octreotide treatment, and WWC3, SERINC1, and ZFAND3 were identified as being correlated with the tumor volume change rate in response to SSA treatment." (PMID 36435867, 2022). "ATP2A2 and ARID5B correlated with the GH change rate in the octreotide loading test, and WWC3, SERINC1, and ZFAND3 correlated with the tumor volume change rate after somatostatin analog treatment." (PMID 36435867, 2022). "The number of cells escaping the tumor mass was significantly increased for ZFAND3 expressing cells, compared to controls." (PMID 33311477, 2020). "We find that in patient samples ZFAND3 expression is increased in infiltrative cells from the tumor margin." (PMID 33311477, 2020). "In conclusion, we identified ZFAND3 as an invasion-related gene that displays increased nuclear expression in the infiltrative tumor compartment of clinical GBM specimen." (PMID 33311477, 2020). "As we found ZFAND3 immunostaining in the nucleus and nuclear localization was increased in the infiltrative tumor compartment, we asked whether nuclear localization was needed for ZFAND3 activity." (PMID 33311477, 2020). "Finally, we evaluated the invasion potential of ZFAND3 KD cell in vivo: eight weeks after intracranial tumor implantation, the mice were sacrified and cell invasion to the contralateral hemisphere was quantified." (PMID 33311477, 2020). "ZFAND3 protein was detected in the majority of GBM (17/21) and throughout different tumor compartments, including central, intermediate and peripheral areas." (PMID 33311477, 2020). "The tumor volume change rate following SSA treatment was correlated with the expression levels of WWC family member 3 (WWC3) and serine incorporator 1 (SERINC1) and tended to correlate with zinc finger AN1-type containing 3 (ZFAND3) expression." (PMID 36435867, 2022).
cancer (1 paper, 2020). A tumor composed of atypical neoplastic, often pleomorphic cells that invade other tissues. "Further elucidation of the molecular determinants of ZFAND3 activity in oncogenic pathways may provide opportunities for targeting cancers, including GBM, prone to locoregional invasion or metastasis." (PMID 33311477, 2020).
ZFAND3 also shares sentences with these, for which no sentence is quoted: Impaired glucose tolerance (1 paper); melanoma (1); pancreatic adenocarcinoma (1).